STAT3 (signal transducer and activator of transcription 3)
Diseases named in the same sentence as STAT3 in open-access papers (continued):
Sharing a sentence is not in itself a finding about the gene and the disease.
multiple myeloma (continued). "Lenalidomide has previously been reported to inhibit phosphorylation of STAT3 in a multiple myeloma cell line, and this was enhanced by the addition of simvastatin." (PMID 23982484, 2013). "The contribution of miR-21 to STAT3 oncogenic activity in myeloma is supported by frequent upregulation of this miRNA in both MGUS and myeloma patients in comparison to healthy donors." (PMID 24416592, 2013). "Atiprimod was also found to be involved in inhibiting STAT3 phosphorylation and inducing apoptosis in multiple myeloma cells U266-B1." (PMID 24199193, 2013). "Recent studies have demonstrated details about the STAT3 nuclear localization mechanism and have blocked this localization in human multiple myeloma cells." (PMID 24098947, 2013). "Other reports show that resveratrol inhibits STAT3 activation in many other cancer cell lines including multiple myeloma, endothelial cells, medulloblastoma, and glioblastoma." (PMID 24199193, 2013). "As2O3 inhibition of STAT3, before inhibition of cellular proliferation, has been described in multiple myeloma cells." (PMID 23382965, 2013). "Overall, the combination treatment of decursin and doxorubicin can enhance apoptotic activity via mTOR and/or STAT3 signaling pathway in multiple myeloma cells." (PMID 23818927, 2013). "In summary, our results demonstrate the synergistic effect of decursin and doxorubicin on the induction of apoptosis via the inhibition of mTOR and/or STAT3 signaling pathway in multiple myeloma cells." (PMID 23818927, 2013). "Stat3 is often constitutively active in many human cancer cells including multiple myeloma (MM), leukemia, lymphoma, and solid tumors." (PMID 22279540, 2012). "Even under normoglycemic/normoxic conditions, PP suppressed the mitochondrial electron-transport chain complex I and thereby STAT3, inhibiting the proliferation of myeloma/erythroleukemia cells." (PMID 23061049, 2012). "Of the STAT proteins, STAT3 is often constitutively activated in many human cancer cells including multiple myeloma, leukemia, lymphoma, and solid tumors." (PMID 22260501, 2012). "In vitro assays demonstrated a critical role of Stat3, a key downstream component of IL-10 signaling, in the survival of human multiple myeloma cells." (PMID 22642622, 2012). "Studies investigating microRNAs in MM began in 2007 with the discovery that interleukin 6 (IL-6) indirectly induces the transcription of miR-21 through signal transducer and activator of transcription 3 (STAT3) transcription in the human myeloma cells line." (PMID 23259069, 2012). "For example, preclinical studies of inhibition of STAT3 by STAT3 inhibitors or JAK2 inhibitors showed potent anti-tumor activity in cancers including solid tumors as well as myeloma." (PMID 22159814, 2012). "We recently reported that Icariside II had the inhibitory effect on STAT3 activation in multiple myeloma cells." (PMID 22493659, 2012). "Our findings demonstrate that EP can exert antitumor activity in multiple myeloma U266 cells by anti-angiogenic activity targeting JAK2/STAT3 signaling pathway as a potent anti-cancer agent for multiple myeloma treatment." (PMID 22260501, 2012). "Immunological inhibitory cytokines, such as TGF-β, IL-10, IL-6 and VEGF, which are produced from myeloma cells, can modulate antitumor host immune response, including the abrogation of DC function, by constitutive activation of STAT3." (PMID 22481968, 2012). "We have previously demonstrated the dephosphorylation of Stat3 and down regulation of its transcriptional activity in response to avicin treatment in myeloma cells." (PMID 22132201, 2011). "Pyrimethamine displays significant activity in vitro against multiple myeloma cell lines characterized by activation of STAT3." (PMID 21680956, 2011). "In leukemias, STAT5 activation upregulates genes critical for tumor survival, whereas in multiple myeloma, STAT3 activates the same, or similar genes, which are critical for the pathogenesis of this tumor type." (PMID 21680956, 2011).
multiple myeloma (continued). "6-OAP abrogates the protective effects of IL-6 and IGF-I on myeloma cells through inhibition of Jak2/Stat3 and Akt signal pathways, respectively." (PMID 21755010, 2011). "Reflecting the importance of this pathway in multiple myeloma (MM), nifuroxazide selectively reduces the viability of MM cells that contain constitutive STAT3 activation." (PMID 21680956, 2011). "Western-blots detected increased p-STAT3 in these CKS1B-silenced myeloma cells compared with untreated, SCR- or CKS1B-shRNA-transfected controls, confirming activation of STAT3 in IGF-1-treated cells." (PMID 20930946, 2010). "SHP1 mediates the inhibition of Stat3 signaling induced by either butein or boswellic acid in multiple myeloma cells." (PMID 20421975, 2010). "Higher concentration (5 μM) of FLLL32 also slightly inhibited the phosphorylation of STAT3 at residue Ser727 in both multiple myeloma cell lines." (PMID 20712901, 2010). "Insulin-like growth factor I (IGF-1) is a well-recognized myeloma cell survival factor activating the STAT3 signaling pathway." (PMID 20930946, 2010). "BMSCs stimulate MAPK signaling in myeloma cells through IL-6R-independent mechanisms thereby circumventing the need for Stat3-mediated signaling in response to IL-6 for myeloma cell survival." (PMID 20204067, 2010). "Cultures of avicin treated myeloma cells showed a decrease in the levels of IL-6, a major inducer of Stat3 activity, which is also known to be under the transcriptional regulation of Stat3." (PMID 19440292, 2009). "IL-6, a major activator of Stat3, particularly in myeloma cells, is known to be under the transcriptional regulation of Stat3 itself, thereby constituting a feedback loop." (PMID 19440292, 2009). "This idea is further supported by the exquisite in vitro sensitivity of multiple myeloma cells, which express high levels of constitutively activated Stat3, to avicins." (PMID 19440292, 2009). "Since Stat3 is constitutively activated in various human tumors besides myelomas, we questioned if avicin D would regulate the Stat3 activity in these tumors too." (PMID 19440292, 2009). "For example, among the STAT family, STAT3 is frequently activated in both multiple myeloma cell lines and tumors derived from patient bone marrows." (PMID 17663801, 2007). "STAT3 activation is required for promotion of tumor cell survival and directly contributes to the malignant progression of multiple myeloma by allowing accumulation of long-lived plasma cells." (PMID 17663801, 2007). "The activation of STAT3 in myeloma cells results in the upregulation of antiapoptotic proteins of the Bcl-2 family, such as Bcl-2, Bcl-XL, and Mcl-1, thus providing MM cells with a survival advantage." (PMID 15970928, 2005). "More recent work has shown that constitutive activation of Stat3 suppresses apoptosis in human multiple myeloma cells." (PMID 11328823, 2001). "The regulatory mechanism of miR-21-5p transcription has been reported to be stimulated by IL-6 and signal transduction and activator of transcription 3 (STAT3) in both human multiple myeloma cell lines and bovine cumulus cells; however, it has never been reported in primary cultured FLS." (PMID 40461641, 2025). "In addition, persistent IL-6/STAT3 signaling can aberrantly reactivate BCL6 expression in IL-6–dependent myeloma cells, fostering uncontrolled proliferation and treatment resistance." (PMID 41357603, 2025). "Additionally, IL-6 stimulation upregulates FGF2 secretion in keratinocytes, myeloma cells, and basal cells through the IL-6/STAT3 pathway." (PMID 38338991, 2024). "Nifuroxazide, an antidiarrheal drug, has been demonstrated to significantly inhibit the activation of Signal Transducer and Activator of Transcription 3 (Stat3) and has also exhibited effects in promoting the death of multiple myeloma cells and inhibiting tumor growth." (PMID 38441416, 2024). "Additionally, TQ inhibited STAT3 phosphorylation in Multiple myeloma cells and MV4-11 leukemia cells." (PMID 37375831, 2023).
multiple myeloma (continued). "Results also showed that UA suppressed myeloma growth through Stat3-mediated inhibition." (PMID 37089712, 2023). "Besides modulating chemoresistance, miR-197-3p targeted Interleukin (IL)-6 and suppressed IL-6/JAK/STAT3 pathways, counteracting the selective proteasome inhibitor Bortezomib’s resistance to multiple myeloma." (PMID 36769824, 2023). "The expression of STAT3 after CpG-STAT3 therapeutics treatment was lower in KMS-11 myeloma cells." (PMID 38067351, 2023). "Similarly in haematological malignancies curcumin has decreased STAT3 activation in multiple myeloma cells, acute myeloid leukaemia and chronic myelogenous leukemia." (PMID 36700235, 2022). "Furthermore, curcumin is a more potent inhibitor than a selective inhibitor of AG490 a selective inhibitor of STAT3 phosphorylation of the JAK2/STAT3 signaling pathway in multiple myeloma cells." (PMID 35883653, 2022). "Additionally, β-caryophyllene oxide suppressed the constitutive activation of STAT3 in multiple tumor cell lines, such as in myeloma, breast and prostate." (PMID 35335182, 2022). "We were also able to confirm once again that STAT3 could be a new molecular target for the treatment of multiple myeloma." (PMID 35503759, 2022). "Another study highlighted that the drug resistance of myeloma cells may be induced through the stimulation of the STAT3 signaling by CKS1B." (PMID 36405738, 2022). "CAMKIIγ activated the ERK/STAT3 signaling pathway in multiple myeloma cells." (PMID 35269900, 2022). "Furthermore, some recent data indicated that IL-32 induced anti-inflammatory cytokines, such as IL-10 and the immunosuppressive molecules such as IDO in macrophages through STAT3 and nuclear factor κB pathway, and promoted multiple myeloma development." (PMID 34414188, 2021). "We then examined several signaling pathways in MSCs, and we observed increased phosphorylation of extracellular signal–regulated kinase 1/2 (ERK1/2), signal transducer and activator of transcription (STAT) 1, STAT3, and Akt in MSCs cocultured with myeloma cells than those in MSCs alone." (PMID 34150666, 2021). "In multiple myeloma, suppression of IL‐6‐mediated STAT3 activation and NF‐kB inhibition could inhibit proliferation, induce apoptosis, and increase chemosensitivity." (PMID 33634982, 2021). "On the other hand, a reduced expression of STAT3 caused a decreased BCL2L1 expression and induced apoptosis, while a functional STAT3 was necessary for BCL2L1 reporter gene activity in myeloma cells, suggesting that STAT3 activity underlies the high expression of Bcl-xL detected in these tumors." (PMID 33803452, 2021). "For example, STAT3-dependent miR-21 transcription was observed in IL-6 stimulated myeloma cells." (PMID 33537096, 2021). "This difference could be explained by the fact, that survival of myeloma cells strictly depends on continuous Interleukin-6 (IL-6) supply and thus on the activation of the STAT3 signaling pathway." (PMID 34531451, 2021). "Therefore, we evaluated mRNA levels ofSOCS3 and its target, STAT3, in the myeloma cell linesafter transfection with the Lentini-off-has-mir-19a-3p vector." (PMID 34837676, 2021). "In addition to the induction of PTPs, 3FC has been described to repress STAT3 activity through the expression of PIAS3 in multiple myeloma cells." (PMID 35053027, 2021). "In a conclusion, lncRNA MSTRG.29039.1 could promote proliferation by sponging hsa-miR-12119 via the JAK2/STAT3 pathway in multiple myeloma." (PMID 34422217, 2021). "There are many important signal pathways in the process of multiple myeloma, such as STAT3 pathway." (PMID 34923957, 2021). "In addition, CD64-expressing neutrophils showed increased ARG1 expression together with p-STAT3 during myeloma progression." (PMID 34960234, 2021). "For instance, a bioinformatics study showed that CCT3 overexpression might affect the progression of multiple myeloma through the JAK/STAT3 pathway." (PMID 34612768, 2021).
multiple myeloma (continued). "It restrained the activation of STAT3 in multiple myeloma cell lines." (PMID 32545187, 2020). "Nevertheless, functions of both, STAiR18 and STAT3, ensure survival of myeloma cells." (PMID 32041604, 2020). "In addition, STAT3 is significantly activated in sorafenib-resistant cells and multidrug-resistant myeloma cells." (PMID 32670862, 2020). "Survival of INA-6 multiple myeloma cells depends on IL-6-mediated STAT3 activation." (PMID 32041604, 2020). "The activated transcription factor STAT3 induces STAiR18 expression in INA-6 myeloma cells." (PMID 32041604, 2020). "Therefore, our preliminary data supported the view that STAiR18 contributes to STAT3-dependent tumorigenesis in multiple myeloma as well as in other cancer entities." (PMID 32041604, 2020). "One such signalling network involved in the pathogenesis of many B cell malignancies is modulated by the transcription factor STAT3 Multiple Myeloma cells are known to be highly dependent on ‘STAT3-mediated’ IL-6 signalling for survival in standard cell culture conditions." (PMID 32098106, 2020). "Ergosterol peroxide also suppressed STAT3–DNA binding in multiple myeloma cells (U266)." (PMID 32545187, 2020). "Thymoquinone inhibited STAT3 phosphorylation in multiple myeloma cells, U266 and RPMI 8226." (PMID 32545187, 2020). "Therefore, the tight interplay of STAT3 and STAiR18 as well as the regulation of their downstream targets turns out to be essential for multiple myeloma cell survival." (PMID 32041604, 2020). "For example, nifuroxazide, a drug used to treat diarrhea, could effectively inhibit JAK2 and TYK2, while decreasing the p-STAT3 levels in multiple myeloma." (PMID 32545187, 2020). "Interestingly, 14–3-3ζ has been reported to regulate STAT3 constitutive activation in multiple myeloma cells." (PMID 30606233, 2019). "It was shown that berberine suppresses interleukin 6 (IL6), a factor required for cell growth in multiple myeloma cells (U266), through negative regulation of the signal transducer and activator of transcription 3 (STAT3), and this induces inhibition of miR-21 expression." (PMID 30987378, 2019). "As miR-21 is an anti-apoptotic factor in cancer cells, STAT3-mediated expression of miR-21 could partly explain the IL-6-induced survival of myeloma cells." (PMID 31130718, 2019). "The anticancer effect of formononetin on human multiple myeloma U266 cells via inhibition of STAT3 pathway was abrogated with the use of antioxidants such as N-acetyl-L-cysteine (NAC) and glutathione (GSH), suggesting that formononetin induces apoptosis via ROS production." (PMID 31402861, 2019). "There is evidence indicated that antagonizing STAT3 signaling could induce cell death in human U266 myeloma cells." (PMID 30847297, 2019). "And inactivation of STAT3 is considered a promising strategy for the treatment of multiple myeloma." (PMID 30302278, 2018). "Along with it, the P-STAT3 levels were reduced, an observation which is in agreement with a previous study showing involvement of integrin β1 in the regulation of STAT3 phosphorylation in myeloma cells." (PMID 29774124, 2018). "Using biotin- and FITC-labeled YL064, we found that YL064 could pull-down STAT3 from myeloma cells and colocalized with STAT3, suggesting that YL064 directly targets STAT3." (PMID 30302278, 2018). "Furthermore, the IL-6/gp130 pathway has been found to induce miR-21 via STAT3-mediated mechanisms in human myeloma cells." (PMID 30068990, 2018). "In conclusion, we identified YL064, a sinomenine derivate, could inhibit cell proliferation and induce cell death in myeloma by directly binding STAT3 and inhibiting its activation." (PMID 30302278, 2018). "Taken together, this study demonstrated that YL064 may be a promising candidate compound for the treatment of multiple myeloma by directly targeting STAT3." (PMID 30302278, 2018).
multiple myeloma (continued). "In the present study, we demonstrate that YL064, a novel sinomenine derivative, could directly inhibit STAT3 activation and induce cell death in myeloma cells both in vitro and in vivo." (PMID 30302278, 2018). "In the bone marrow environment, cytokines such as IL-6, secreted by stromal cells or the myeloma cells, could lead to the constitutive activation of STAT3." (PMID 30302278, 2018). "Since STAT3 is constitutively active in multiple myeloma cell lines and contributes to chemoresistance, these findings may have a great significance in the therapy of multiple myeloma." (PMID 28208828, 2017). "In addition, it was reported that berberine suppresses multiple myeloma cell growth by reducing miR-21 through IL6/Stat3 regulation." (PMID 29113353, 2017). "Given the pivotal role of STAT3 in multiple myeloma initiation and progression, the aim of our study was to investigate whether GAC 17:1 can exert its anti-tumor activity through the attenuation of the STAT3 signaling pathway in multiple myeloma cells." (PMID 28208828, 2017). "In addition, it was found that inhibition of GSK‐3 increases NKG2D ligand MICA expression in multiple myeloma cells via a down‐regulation of STAT3 activation." (PMID 28165192, 2017). "The two sites we identified are supposed to mediate STAT3-dependant transcription in myeloma cells." (PMID 29100302, 2017). "Overall, these results demonstrate that GAC 17:1 could be an effective anticancer agent that is predominantly safe and can act as a novel blocker of STAT3 activation in multiple myeloma." (PMID 28208828, 2017). "This study focused on the role of IL-10 in MM cell line proliferation and resistance to anticancer drugs, considering that there are numerous reports on the role IL-6 in survival and proliferation of multiple myeloma (MM) cells through the phosphorylation of STAT3." (PMID 27418139, 2017). "Additionally, IL-6 induced STAT3 phosphorylation in U266 multiple myeloma cells were found inhibited by TQ along with c-Src and JAK-2 activation." (PMID 28983249, 2017). "IL-6 upregulates Mcl-1 expression via activated STAT3 signaling in myeloma cells." (PMID 29340073, 2017). "Taken together, this study identified a novel oral JAK2/STAT3 inhibitor that could be developed as an anti-myeloma agent." (PMID 26814430, 2016). "In this study, we show that reelin produced by MM cells promotes the adhesion of tumor cells to fibronectin via activation of integrin β1-FAK pathway and the subsequent activation of Akt and STAT3 signaling molecules, eventually facilitating the survival and drug resistance of myeloma cells." (PMID 26848618, 2016). "For instance, STAT3 is constitutively activated in multiple myeloma patients." (PMID 26972355, 2016). "STAT3 has also been considered to be a target for the induction of apoptosis in tumor cells and Gossypol, a cotton plants extraction, has been found to induce apoptosis in myeloma cells by inhibiting phosphorylation of JAK and STAT3." (PMID 25781885, 2015). "Therefore, our data suggests that a combination of rafts target drug with JAK/STAT3 inhibitor seems to be a very promising approach for myeloma therapeutic intervention." (PMID 25781885, 2015). "This concept has been explored to enhance immune responses in hematopoietic cancers, whereby targeting STAT3 specifically in TLR9 expressing cancer cells can be achieved using CpG based delivery of silencing oligos results in growth inhibition of myeloma and myeloid leukemia." (PMID 24722453, 2014). "Down-regulation of interleukin 6 (IL6) by berberine might lead to inhibition of miR-21 transcription through STAT3 down-regulation in multiple myeloma." (PMID 25000828, 2014). "In human, multiple myeloma cells thymoquinone inhibited proliferation, induced apoptosis, and induced chemosensitization, through suppression of the signal transducer and activator of transcription 3 (STAT3) activation pathway." (PMID 25401162, 2014).